CD47 (CD47 molecule)
Diseases named in the same sentence as CD47 in open-access papers (continued):
Sharing a sentence is not in itself a finding about the gene and the disease.
tumor (continued). "This contrasting impact of macrophage abundance on patient prognosis suggests that CD47-mediated signaling maintains TAMs in a pro-tumor functional status." (PMID 39994810, 2025). "Here, we discovered positive correlations between tumor CD47 expression and fecal SCFA contents, particularly butyrate." (PMID 39994810, 2025). "Macrophage-targeted checkpoint inhibitors, including SIRPα inhibitors (which block the tumor CD47 “don’t eat me” signal), are being evaluated in OC." (PMID 40643516, 2025). "In this study, we combined low-affinity CD47 checkpoint blockade and specific tumor targeting in a multivalent and multifunctional antibody construct to prevent CD47-related toxicities." (PMID 40402266, 2025). "To clarify the molecular mechanisms involved, we generated tumor-infiltrating Treg cells with stable CD47 overexpression via lentiviral transduction and analyzed their protein expression by Western blot." (PMID 41402667, 2025). "In summary, CD47–SIRPα signaling enables tumor cells to avoid macrophage-mediated clearance, making it a key innate immune checkpoint and an attractive therapeutic target." (PMID 41514569, 2025). "Multiple studies have demonstrated that blockade of CD47 enhances phagocytosis and antigen-presenting capabilities of macrophages and neutrophils, thus activating tumor-specific T cells and consequently stimulating adaptive immune responses." (PMID 41383500, 2025). "In vivo, combining LSD1 inhibitors with anti-CD47/PD-L1 antibodies in TC-1 tumor-bearing mice significantly inhibits tumor growth by enhancing immune activation and reducing CD47 and PD-L1 signaling." (PMID 41029427, 2025). "Blocking the CD47–SIRPα axis with monoclonal antibodies facilitates macrophage activation and tumor clearance." (PMID 40800581, 2025). "The combination of IR700@Nb289‐OMVs with CD47 blockade not only significantly repressed primary and metastatic tumours but also partially eliminated them and produced durable antitumour immune memory." (PMID 40240911, 2025). "When combined with CD47 inhibitors (e.g., anti-CD47 monoclonal antibodies), the CD47-SIRPα signaling axis on tumor cells is blocked, lifting the inhibitory signals on TANs and significantly enhancing their phagocytic efficiency." (PMID 40568594, 2025). "To further validate the specific binding and distribution of CD47 in EC tissues, we analyzed a specimen by preparing frozen sections of both the fluorescent tumor lesions and the surrounding non‐cancerous tissue." (PMID 40385528, 2025). "B7-H3 is believed to limit T cell entry and support tumor growth, while CD47 serves as a “don’t eat me” signal that stops the immune system from attacking tumor cells." (PMID 41012160, 2025). "Anti-CD47 antibodies combined with CAR-NK cells demonstrated robust anti-tumor activity in gastrointestinal cancer models." (PMID 41511303, 2025). "The combination of HMGA2 inhibitors and targeted macrophage immunotherapy (CD47 monoclonal antibody) had the better tumor suppression effect." (PMID 40703517, 2025). "Discovered as the first tumor phagocytosis checkpoint at the end of the 21st century, blocking the CD47-SIRPα axis or combining it with other therapies has been proven to be a promising treatment strategy in cancer immunotherapy." (PMID 40129966, 2025). "Blocking CD47 with agents such as CV1 can enhance macrophage function to engulf tumor cells, making it a promising strategy for cancer therapy." (PMID 40487639, 2025). "This interaction is further confirmed by immunohistochemical (IHC) analysis, which revealed that CD47+ tumor cells locate in proximity to SIRPA+ macrophages." (PMID 41450739, 2025). "A recent study demonstrated that THBS2 secreted by cancer-associated fibroblasts (CAFs) promotes CRC progression by binding to CD47 on tumour cells and activating the MAPK/ERK5 signalling cascade." (PMID 40860666, 2025).
tumor (continued). "IgA monoclonal antibodies (mAbs) can activate neutrophils to kill tumor cells; this can be further enhanced by blocking the myeloid immune checkpoint CD47." (PMID 40358156, 2025). "LSD1 exerts direct and indirect regulatory effects on immune checkpoints, notably CD47 and PD-L1, which mediate tumor immune escape via the SIRPα/CD47 and PD-1/PD-L1 pathways, respectively." (PMID 41029427, 2025). "CD47/SIRPα blockade disrupts the “don’t eat me” signal, enabling macrophages to phagocytose tumor cells." (PMID 40643516, 2025). "The mechanism behind the efficacy of CD47 blockade is largely attributed to the improved activity of APCs, which led to improved anti-tumor T cell responses." (PMID 41322194, 2025). "Functional studies showed that Hu1C8 exhibited similar activity to other anti-CD47 antibodies in the clinical stage by promoting tumor cell phagocytosis in vitro and exerting antitumor effects in vivo." (PMID 40578556, 2025). "These hGLVs, which overexpress CD47, exhibited extended circulation times and enhanced macrophage-mediated phagocytosis of tumor cells by inhibiting CD47 signaling." (PMID 40317075, 2025). "Blocking the CD47–SIRPα interaction using mAbs enhances macrophage-mediated phagocytosis of tumor cells, thereby suppressing tumor growth." (PMID 40508202, 2025). "Tumor-derived EVs also express CD47, a protein found on tumor cells that normally binds to signal regulatory protein alpha (SIRPα) on macrophages to inhibit phagocytosis." (PMID 40006624, 2025). "Of these, NIH3T3 cells, which are the non-tumor-derived cell line and express the highest levels of CD47, exhibit minimal phagocytosis by RAW264.7 cells, and the effects of MCS and the anti-CD47 antibody magrolimab were also not observed." (PMID 39744689, 2025). "Mechanistically, HDACi impaired the phagocytic capacity of macrophages against tumor cells through epigenetically upregulating CD47 expression." (PMID 39994810, 2025). "Blocking CD47 with monoclonal antibodies promotes phagocytosis of tumor cells mediated by DCs, which in turn enhances antigen cross-presentation and activation of cytotoxic T Cells." (PMID 40356601, 2025). "The combination of BNCT and CD47 blockade significantly improved the survival rate of tumor-bearing mice." (PMID 41179690, 2025). "Another justification stems from pairing PARPi with anti-CD47 or anti-SIRPα therapies to reduce phagocytic thresholds and drive the additional myeloid presence towards effective tumor elimination and cross-priming of T cells." (PMID 41488638, 2025). "The GPC3/CD47 bispecific antibody co-targets a tumor antigen and the “don’t eat me” signal, namely the CD47–SIRPα pathway." (PMID 41375072, 2025). "The CD47/SIRPα pathway is a critical mechanism by which tumors evade macrophage detection, and CD47 is a transmembrane protein that is often expressed on the surface of tumor cells." (PMID 40270598, 2025). "The results of FCM analysis showed that the phagocytic activity of CAR-Ms on CT26 tumor cells was significantly improved after oAd-CD47 treatment." (PMID 40814015, 2025). "The gene delivery and immunostimulatory abilities of the DMPLAC vector were further studied, and the anticancer ability of the DMPLAC/CD47 complex in several mouse tumor models, such as subcutaneous and abdominal tumor models, was evaluated." (PMID 40006507, 2025). "CD47 inhibition combined with RT yields greater tumor clearance than either treatment alone, consistent with enhanced T cell infiltration as described." (PMID 41296731, 2025). "Activation with CpG oligodeoxynucleotide, a Toll-like receptor 9 agonist, reshapes macrophage metabolism, allowing macrophages to overcome tumor cell CD47-mediated inhibition." (PMID 39941865, 2025). "A pivotal mechanism of immune evasion is orchestrated by the CD47-SIRPα axis, whereby tumor cells upregulate the "don't eat me" signal CD47 to engage the inhibitory receptor SIRPα on tumor-associated Mφs (TAMs) and suppress phagocytosis." (PMID 41164198, 2025).
tumor (continued). "For example, radiotherapy upregulates CD47 on tumor cells and SIRPα expression on myeloid cells in colorectal cancer." (PMID 40835598, 2025). "Anti-CD47 therapies have been demonstrated to significantly enhance macrophage phagocytosis and suppress tumor growth, highlighting its potential as a promising therapeutic target." (PMID 40396172, 2025). "Overall, this study has reinforced the link between OV-mediated inflammation and CD47 expression, highlighting this as an opportunity to enhance innate and downstream adaptive anti-tumor immune responses." (PMID 41322194, 2025). "Blockade of N111 glycosylation represses CD47 expression and promotes macrophage phagocytosis of tumor cells." (PMID 41355073, 2025). "Compared with monotherapy (either ouabain or CD47 Ab), the combo treatment further minimized the tumor volume." (PMID 40985476, 2025). "Apart from preventing macrophage phagocytosis, the elevated CD47 expression in tumor cells also reciprocally increased the M2-like phenotype of macrophages." (PMID 39994810, 2025). "Western blot analysis confirmed the successful expression of the anti-CD47 antibody in tumor cells following infection with oAd-CD47." (PMID 40814015, 2025). "Targeted editing of key nodes—including MerTK, CD47, and SIRPα—enhances phagocytic capacity and potentiates antitumor immunity in preclinical tumor models." (PMID 41403915, 2025). "For example, acid/enzymatic dual—responsive nanovesicles co—delivering oxaliplatin and photosensitizers, in combination with anti—CD47 antibody, can notably enhance tumor suppression rates and induce long—lasting immune memory." (PMID 40877572, 2025). "Monoclonal antibodies targeting CD47 have been shown to block this immunosuppressive interaction, successfully inducing antibody-dependent cellular phagocytosis of tumor cells in diverse preclinical tumor models." (PMID 40563367, 2025). "The tumor mass exhibited a similar trend to the volume of xenograft tumors among each group, demonstrating that the simultaneous neutralization of CD47 is required for yielding the optimal therapeutic outcome of HDACis." (PMID 39994810, 2025). "Numerous studies have demonstrated that CD47 is selectively enriched in the CSC population compared to bulk tumor cells in various malignancies, including AML, lung, bladder, hepatic, colorectal, pancreatic, ovarian, esophageal and breast cancer." (PMID 41233805, 2025). "CD47/SIRPα blockade is expected to enhance the phagocytic activity of TAMs against cancer cells and exert effective anti-tumor activity." (PMID 40508145, 2025). "The tumour suppression effect of CAR-iMACS was even more pronounced by adding anti-CD47 or anti-programmed cell death protein-1 (PD1) immune checkpoint inhibitors in the treatment regimen." (PMID 40574837, 2025). "CD47 functions by inhibiting macrophage phagocytosis of tumor cells through its binding to signal regulatory protein α (SIRPα) on the surface of macrophages, thereby promoting tumor growth and metastasis." (PMID 39781344, 2025). "The RGD modification provided tumor targeting and CD47 avoided the mononuclear phagocyte system (MPS)." (PMID 40475972, 2025). "This pathway is regulated by metabolic cues, such as ROS and lipid metabolism, which induce CD47 expression in tumor cells." (PMID 41394868, 2025). "Beyond inhibiting phagocytosis, CD47 influences antigen presentation, T cell activation, and tumor angiogenesis, highlighting its broader role in immune evasion." (PMID 41303525, 2025). "CD47 enhances the ability of tumor cells to evade macrophage phagocytosis by participating in SIRPα." (PMID 40548122, 2025). "The synergistic effect of HDACis and CD47 neutralizing antibody was assessed in subcutaneous murine tumor models." (PMID 39994810, 2025). "Another critical immune checkpoint, CD47–SIRPα, acts as a “don’t eat me” signal to macrophages, preventing the phagocytosis of tumor cells." (PMID 41394868, 2025).
tumor (continued). "CD47-SIRPα checkpoint blocking therapies have shown minimal anti-tumor efficacy when used alone as a monotherapy, yet profound activity in combination with therapeutic human mAb." (PMID 40408355, 2025). "Mathematically, this is because IR directly targets the tumor populations, while anti-CD47 affects their derivatives, thus limiting the overall therapeutic effect." (PMID 40845580, 2025). "One cycle of IR700@Nb289‐OMV plus NIR or two injections of the CD47 nanobody alone showed similar tumour inhibitory efficacy." (PMID 40240911, 2025). "Following intravenous administration, FeSR780@CAT@Mex-RS17 accumulated at tumor sites owing to its innate homing ability and affinity for CD47 on tumor cells." (PMID 40051791, 2025). "It has also been found that caerin 1.1/1.9 upregulates CD47 on tumor cells; the combination of caerin 1.1/1.9 intratumor injection, CD47 blockade, and therapeutic vaccination (triple therapy, TT) significantly prolonged survival in B16 tumor-bearing mice." (PMID 40573908, 2025). "CD163+ macrophages remain responsive to CD47 blockade, making them promising immunotherapy targets in OC despite tumor-induced immunosuppression." (PMID 41280929, 2025). "Upon binding to SIRPα, CD47 transmits an inhibitory signal that prevents phagocytosis, thereby allowing tumor cells to evade immune surveillance." (PMID 40765033, 2025). "Blocking CD47–SIRPα has demonstrated promising effects in curbing tumor growth by increasing macrophage phagocytosis and stimulating CTL cross-presentation of antigens." (PMID 40051791, 2025). "When combined with CD47 blockade antibody (αCD47), this approach markedly suppressed tumor growth, metastasis, and recurrence, highlighting the promising potential of nanoplatforms in chemo‐IT combinations." (PMID 40900811, 2025). "The hybrid system was developed by fusing cRGD-modified liposomes loaded with miR-497 and triptolide with CD47-expressing tumor-derived exosomes." (PMID 40182844, 2025). "CD47 is often overexpressed on tumor cells, where it binds to SIRPα on macrophages to transmit an inhibitory “do not eat me” signal that suppresses phagocytosis and promotes immune evasion." (PMID 41402667, 2025). "CD47 is a “don’t eat me” signal expressed on tumor cells to prevent phagocytosis by tumor macrophages." (PMID 41415295, 2025). "These strategies fall into three principal categories: depletion of TAMs, reprogramming toward anti-tumor phenotypes, and blockade of the CD47–SIRPα axis." (PMID 41142826, 2025). "Inhibiting the CD47/SIRPα interaction between macrophages and tumor cells has the potential to restore macrophage-driven anti-tumor immune responses mediated by TAMs." (PMID 40607438, 2025). "CD47 interacts with SIRPα on the surface of macrophages, effectively suppressing macrophage-mediated phagocytosis of tumor cells." (PMID 40003951, 2025). "Previous studies have highlighted the role of CD47 as a “don’t eat me” signal, helping tumor cells evade phagocytosis by macrophages, which has led to its consideration as a potential therapeutic target." (PMID 40104289, 2025). "Simultaneously, it has the potential to block the SIRPα-mediated non-CD47-dependent pathway, reprogramming the suppressive tumor immune microenvironment." (PMID 40589735, 2025). "QPCT was 58-fold overexpressed; its isoform QPCTL has been reported to activate CD47 on tumor cells, leading to inhibition of phagocytosis by immune cells." (PMID 40717170, 2025). "Our previous research demonstrated that CD47 expression in tumour cells partially accounts for its effect on macrophage infiltration within the tumour microenvironment (TME)." (PMID 41163221, 2025). "The blockade of CD47 disrupts this interaction, promoting macrophage-mediated clearance of tumor cells." (PMID 40806636, 2025). "These tumor cells engage the SIRPα-CD47 axis to inhibit antigen-presenting cell phagocytosis, while glycolytic metabolites polarize TAMs toward M2 phenotypes, which secrete IL-10 to dampen immune responses." (PMID 40959090, 2025).
tumor (continued). "Tumor cells exploit immune checkpoint molecules (ICMs), like PD-L1 and CD47, to escape macrophage-mediated surveillance." (PMID 40761779, 2025). "Tumor cells frequently overexpress CD47, a “Don’t Eat Me” signal that binds to SIRPα on macrophages, inhibiting phagocytosis." (PMID 39982231, 2025). "CD47, often overexpressed on tumor cells, serves as a “don’t eat me” signal by engaging SIRPα on macrophages to suppress phagocytosis." (PMID 40800581, 2025). "Disrupting “don’t eat me” signals by targeting the CD47-SIRPα axis enhances TAM-mediated phagocytosis of tumor cells." (PMID 40177538, 2025). "This modular domain is responsible for recognising tumour-associated antigens such as CD19, human epidermal growth factor receptor 2 (HER2), and CD47, which are commonly expressed in tumour tissues." (PMID 40574837, 2025). "CD47 expression in tumor cell lines and patient-derived organoids was evaluated by quantitative polymerase chain reaction (QPCR) and flow cytometry." (PMID 39994810, 2025). "Together, these findings suggest that IL-8/CXCR2-induced metabolic reprogramming promotes CD47 expression by increasing AC-CoA levels, which increases p65 acetylation and subsequent NF-κB pathway activation, thereby supporting tumour immune evasion." (PMID 41163221, 2025). "Many studies have confirmed that anti‐CD47 antibody can recover macrophage‐mediated phagocytosis in cancer and enhance an anti‐tumor T‐cell immune response." (PMID 41354057, 2025). "The biodistribution of CAR-Ms in CT26 tumor-bearing mice corroborated these results, with the accumulation of CAR-Ms in the tumor of mice intratumorally injected with oAd CD47 increased." (PMID 40814015, 2025). "It is now feasible to successfully suppress tumor cell growth and metastasis by inhibiting CD47-SIRPα signaling, restoring macrophage phagocytosis of tumor cells, and enhancing the effector CD8+ T cell response." (PMID 41019045, 2025). "In the same way as in the anti-CD47, we do this by modifying the value of the tumor killing parameter μ upon CSF-1R inhibition treatment." (PMID 40845580, 2025). "Preclinical human tumor models have extensively examined the efficacy of CD47-blocking monoclonal antibodies, which can induce antitumor responses mediated by CD8+ T cells." (PMID 41350707, 2025). "Treatment with anti-CD47 alone in silico provided some benefit compared to untreated mice; however, its effect on reducing tumor volume was minimal, and much smaller than IR effect (Cohen’s d = −0.9 [−3.1, −0.5])." (PMID 40845580, 2025). "The exosomes are then internalized by the tumor cells, releasing their dual cargo—Cisplatin and an anti-CD47 antibody." (PMID 40869279, 2025). "This system not only suppresses the “don’t eat me” signals mediated by CD47 but also drives phagocytic M1 polarization, thereby enhancing macrophage-mediated tumor cell clearance." (PMID 41355895, 2025). "Addition of CD47 blockade enhanced lysis of the highest mAb concentration by 2.3 fold for the tumor cells and sixfold for Panc 10.05." (PMID 40358156, 2025). "One advantage of antibody-based approaches over gene knockout approaches is that previous work has shown that blocking CD47 with an intact Fc portion promotes anti-tumor activity through antibody-dependent cellular phagocytosis." (PMID 40082557, 2025). "A primary concern is on-target, off-tumor toxicity resulting from CD47 expression on red blood cells (RBCs)." (PMID 41179296, 2025). "For example, anti-CD47 antibody-regulated phagocytosis of tumor cells by macrophages primes the proliferation of CD8+ T cells both in vitro and in vivo and lead to reduction of FoxP3+ regulatory T cells (Tregs) in vitro." (PMID 40070841, 2025). "The analysis revealed that the protein level of CD47 was significantly elevated in tumor tissues compared with normal tissues." (PMID 40548645, 2025).